USP3 (ubiquitin specific peptidase 3)
Diseases named in the same sentence as USP3 in open-access papers (continued):
Sharing a sentence is not in itself a finding about the gene and the disease.
rheumatoid arthritis (1 paper, 2024). A chronic, systemic autoimmune disorder characterized by inflammation in the synovial membranes and articular surfaces. "USP5 can also stabilize TRAF6 by deubiquitination, but contrary to the results of USP3, overexpression of USP5 increases the activation of NF-κB pathway, promotes the release of NF-κB, and then up-regulates the secretion of pro-inflammatory cytokines such as IL-1β in rheumatoid arthritis (RA)." (PMID 40226783, 2024).
tumor (19 papers, 2015 to 2026). "We also observed that higher expression of USP3 was positively associated with stronger expression of SMARCA5 in tumor tissues." (PMID 39500888, 2024). "In conclusion, these findings indicate that Aurora A and USP3 are highly expressed in human ESCCtissues and are associated with poor tumor grade." (PMID 34758762, 2021). "Results from other studies also support the conclusion that overexpression of USP3 increases tumour proliferation and is associated with the progression of GC." (PMID 34930901, 2021). "Additionally, the loss of USP3 led to a decrease in tumor size in a mouse xenograft model, whereas the tumor size was increased in mice injected with USP3-depleted cells reconstituted with either USP3 or REST." (PMID 37170124, 2023). "Moreover, decreased USP3 mRNA expression in primary CRC has been associated with advanced tumour stage and distal metastasis." (PMID 28655924, 2017). "Such broad spontaneous neoplasia in USP3-deficient mice might be linked to enhanced genomic instability, as observed in primary MEFs form these animals." (PMID 26442100, 2015). "Effects of USP3 on the progression of GC in vivo and in vitro and the potential underlying mechanisms have been investigated utilizing proteomics, RT-PCR, western blotting, immunohistochemistry, immunofluorescence, cell invasion and migration assays and xenograft tumor models." (PMID 31234902, 2019). "Functional assays show that USP3 knockdown suppresses cell proliferation, colony formation, and cell-cycle progression, whereas USP3 overexpression reverses these phenotypes and significantly accelerates tumor growth in nude-mouse xenografts." (PMID 41301681, 2025). "USP3, a deubiquitinating enzyme, affects tumor progression by participating in the regulation of multiple cellular activities." (PMID 38531846, 2024). "Depletion of USP3 or docetaxel treatment similarly inhibited tumor growth, whereas the combined silencing of USP3 and docetaxel treatment did further reduce tumor growth in the xenograft model." (PMID 39500888, 2024). "USP3 protein and mRNA expression was elevated in PCa tissues compared with adjacent non-tumor tissues." (PMID 39500888, 2024). "Next, we analyzed the expression of USP3 protein in tissue microarray containing 100 samples of PCa tissues and 99 samples of adjacent non-tumor tissues by Immunohistochemical (IHC) analysis." (PMID 39500888, 2024). "USP3 knockdown inhibited tumor growth, while co-overexpression of SMARCA5 significantly rescued this effect." (PMID 39500888, 2024). "USP3 regulates various tumor-related activities, such as cell proliferation, cell cycle and DNA damage repair." (PMID 38531846, 2024). "In the subcutaneous tumor formation model, we observed that the tumor volume was smaller in the USP3 knockdown group than in the control group." (PMID 38531846, 2024). "USP3, as a deubiquitinating enzyme, mediates tumor progression mainly by deubiquitinating and modifying downstream target proteins." (PMID 38531846, 2024). "Immunohistochemical staining of excised tumor sections revealed that the expression level of Ki67 protein, a marker of proliferation, was significantly lower in the USP3 knockdown group than in the control group." (PMID 38531846, 2024). "Silencing of USP3 blocks the epithelial-mesenchymal transition resulting in drastic inhibition of migration, invasion, and tumor growth in GBM cells." (PMID 37170124, 2023). "The expression of OTUB1 and UCHL5 was significantly decreased (p < 0.001) in AS, GBM, and ODG compared to non-tumor tissue, while the expression of USP3 was significantly elevated (p < 0.001)." (PMID 37892185, 2023). "ELF5 acts as a tumor suppressor though activating the transcription of USP3 to stabilizing WDTC1 in RCC." (PMID 37980532, 2023). "The mice injected with USP3-KO cells displayed a significant reduction in tumor volume and weight compared to mice injected with mock cells." (PMID 37170124, 2023).
tumor (continued). "The ubiquitination modification site and the regulatory effect of USP3 on centrosome and tumor function have yet to be reported." (PMID 34758762, 2021). "In conclusion, our study revealed a mechanism that accounted for the tumour-driver function of USP3 in GC progression." (PMID 34930901, 2021). "Our previous work has demonstrated that in GC, USP3 expression is abnormally high in tumours and promotes epithelial-to-mesenchymal transition (EMT), invasion, and metastasis of cancer cells by deubiquitinating SUZ12." (PMID 34930901, 2021). "In HeLa cells, it was seen that USP3 knockdown led to a reduction in CDC25A phosphatase levels, causing a delay in cell cycle progression and a reduction in tumor growth in mice xenografts." (PMID 34577547, 2021). "Given the important role of multiple DUBs in cancer-associated signaling pathways, little is known regarding the roles of USP3 and Aurora A in tumor invasion and metastasis." (PMID 34758762, 2021). "We also observed that higher expression of USP3 was associated with stronger expression of COL9A3 and COL6A5 in tumour tissues." (PMID 34930901, 2021). "We collected tumour tissues and corresponding normal tissues of gastric mucosa from 12 GC patients and detected the expression of USP3, COL9A3, and COL6A5 by western blotting." (PMID 34930901, 2021). "USP3 has served as a deubiquitinase of Cdc25A and accelerated tumour proliferation, resulting in poor prognosis in patients with breast cancer." (PMID 34930901, 2021). "In conclusion, we found an associated lncRNA network that regulates the tumour cell development network, consisting of lncRNA HOXA‐AS3, miR‐455‐5p and USP3." (PMID 32918360, 2020). "USP3 knock out (KO) cells were interrupted to preserve chromosome integrity and USP3 KO mice promote tumor development." (PMID 31700696, 2019). "For example, in one study, USP3 was overexpressed in GC tissues and cells, and ectopic USP3 promoted GC tumor growth." (PMID 31234902, 2019). "And knockdown of EPHA2 expression reversed the pro-tumour effects of USP3-upregulating." (PMID 38531846, 2024). "Furthermore, the immunohistochemical (IHC) analysis of mouse xenograft tumor tissues showed a significant reduction in USP3 and REST expression in USP3-depleted tumors relative to mock control tumors." (PMID 37170124, 2023). "However, transplantation of USP3-depleted cells reconstituted with either USP3 or REST resulted in a significant increase in tumor weight and volume." (PMID 37170124, 2023). "Recent progress has highlighted the significance of USP3 in tumor progression." (PMID 31234902, 2019). "Besides, we observed that reduced USP3 expression was remarkably correlated with advanced tumour stage in three other CRC datasets (GSE39582, GSE14333 and GSE33193)." (PMID 28655924, 2017). "As a sponge of miR-224, the USP3 3′UTR may be a promising miR-224 inhibitor that could be applied in CRC gene therapy to inhibit tumour progression in the near future." (PMID 28655924, 2017). "Notably, analogously to RNF8, Usp3-deleted mice develop a broad spectrum of tumor types with a latency of 1 year of age." (PMID 26442100, 2015). "Interestingly, USP3 may play an integral role in acute myeloid leukemia as a tumor suppressor by regulating H2AK119u in 12-O-tetradecanoyl phorbol-13-acetate (TPA)-induced differentiation of HL-60 cells, which offers a prospective therapeutic approach." (PMID 38773075, 2024). "The aberrant expression of USP3 may have an important role in tumor development." (PMID 31234902, 2019). "In solid tumors, USP3 is significantly upregulated in gastric cancer, glioblastoma, and breast cancer, where it stabilizes oncoproteins (e.g., c-Myc, MDM2) to promote tumor proliferation, metastasis, and therapy resistance." (PMID 41301681, 2025). "In GBM, the transcription factor Snail plays a crucial role in USP3-mediated EMT, promoting cell invasion, migration, and tumor progression." (PMID 38773075, 2024).
tumor (continued). "To further investigate the effects of the USP3-COL9A3/COL6A5 axis on tumour metastasis in GC in vivo, we established BGC-823 cells stably depleting USP3 by lentiviral transfection, with simultaneous overexpression of COL9A3 or COL6A5." (PMID 34930901, 2021). "Immunoblot analysis of snap-frozen tumor tissues showed a decrease in ALYREF, USP3, and MYCN protein expression as a result of doxycycline treatment, compared to vehicle control." (PMID 33767157, 2021). "Previous studies, including our own recent work, identified DUBs (Dub3, USP3, and HAUSP) involved in Cdc25A-dependent cell cycle and tumor progression." (PMID 34071237, 2021). "Moreover, we further analysed USP3, COL9A3 and COL6A5 expression in tumour samples and adjacent normal tissues from 94 GC patients using TMA, along with their corresponding clinicopathologic information." (PMID 34930901, 2021). "On the other hand, USP3 was highly expressed in ESCC but did not have a significant correlation with tumor grade." (PMID 34758762, 2021). "Notably, a high USP3 expression was also correlated with larger tumor size and poor histological grade but not correlated with age and Lymph node metastasis." (PMID 39500888, 2024).
cancer (17 papers, 2015 to 2025). A tumor composed of atypical neoplastic, often pleomorphic cells that invade other tissues. "Recent studies showed that USP3 is highly expressed in a variety of malignancies and is associated with a series of malignant biological behaviors of cancers, and also plays a key role in DNA damage response." (PMID 39500888, 2024). "USP3 demonstrates abnormal expression in various cancer types and contains multiple mutation sites, in addition to its involvement in the pathogenesis of several other diseases." (PMID 38773075, 2024). "Depletion of USP3 leads to loss of cell–cell contacts and motility, indicating its role in adjusting cancer cell activity." (PMID 31700696, 2019). "The results showed that the USP3 expression levels were significantly higher in various cancer tissues than in normal tissues." (PMID 38531846, 2024). "As USP3 and SMARCA5 were required for DNA repair, which has a key role in human cancer, it is possible that USP3 promotes deubiquitination and stabilization of SMARCA5 in PCa specimens." (PMID 39500888, 2024). "USP3 exhibits aberrant expression in various cancers, suggesting its significant role in cancer progression." (PMID 38773075, 2024). "Based on our observation of the silencing of USP3 promoting RA-induced differentiation, we envision that targeting USP3 along with retinoids is likely to enhance retinoid therapy in several cancer types." (PMID 37170124, 2023). "USP3 has been identified to have deubiquitination activity during cell activity in various malignant tumors." (PMID 37980532, 2023). "According to literature review, USP3 can mediate protein deubiquitination by acting as a deubiquitinase to promote protein expression and regulate cancer progression." (PMID 35739527, 2022). "For example, there are some DUBs that are only identified in the cancer cells like USP3, USP4, and OTUD7B." (PMID 33718328, 2021). "Ubiquitin-specific protease 3 (USP3), a member of the USP family, is highly expressed in a variety of malignancies and is associated with a series of malignant biological behaviours of cancers." (PMID 34930901, 2021). "In this study, we report on USP3, a gene that is overexpressed in various cancers, including GC and that acts as an important oncogene." (PMID 31234902, 2019). "Next, the expression of USP3 was detected in six cancer cell lines by semiquantitative RT-PCR assay." (PMID 31234902, 2019). "To test whether the potential role of the USP3-SMARCA5 axis may as a target for cancer therapy, we silenced USP3 or SMARCA5 individually or together in PC3 cells or DU145 cells (B: left), and examined the cell survival following docetaxel." (PMID 39500888, 2024). "The important function of USP3 in malignant tumors has been confirmed by some studies." (PMID 37980532, 2023). "USP3 plays a key role in regulating diverse biological functions in cancers." (PMID 37170124, 2023). "In recent years, an increasing number of studies have shown that USP3 is involved in the development of several tumors, and it is consequently essential to investigate the regulatory mechanisms of USP3 in cancer, which may provide us with evidence for the development of USP3 inhibitors." (PMID 38773075, 2024). "In NPC, the LINC01605/miR-942-5p/Ikbkb ceRNA network modulates cancer cell behavior, with LINC01605 facilitating the recruitment of IGF2BP2 to stabilize USP3." (PMID 38773075, 2024). "Semi-quantitative scoring showed that USP3, COL9A3 and COL6A5 proteins were expressed at significantly higher levels in cancer tissues than in adjacent normal tissues." (PMID 34930901, 2021). "We found that USP3 and SUZ12 were expressed at high levels in the nucleus and cytoplasm of cancer cells from two patients." (PMID 31234902, 2019). "Here, I will focus on the emerging roles of the H2A DUBs USP3, USP16, USP44, BAP1, and MYSM1 in HSC maintenance and cancer." (PMID 26442100, 2015).
cancer (continued). "Smo inhibition sensitizes cancer cells to radiation, as in this situation, USP3 is not expressed, and Claspin is polyubiquitylated and degraded in the proteasome." (PMID 41009395, 2025). "In addition, we evaluated the expression of USP3 and REST in different cancer tissues using the Correlation AnalyzeR." (PMID 37170124, 2023). "Semiquantitative scoring showed that USP3 protein was expressed at significantly higher levels in cancer tissues compared with adjacent nontumor tissues." (PMID 31234902, 2019). "Nevertheless, the impact of USP3 on cancer development has not previously been reported." (PMID 28655924, 2017). "USP3 and SUZ12 were only expressed in cancer cells, whereas E-cadherin was predominantly expressed in normal epithelial cells." (PMID 31234902, 2019).
haematopoietic cancer (2 papers, 2017 to 2023). "The USP3-insufficient mice have a shorter lifespan and an increased risk of developing hematopoietic cancer." (PMID 37980532, 2023). "USP3-deficient mice present significantly shorter life spans and an increased haematopoietic cancer incidence." (PMID 28655924, 2017).
neurological disease (1 paper, 2021). "Importantly, inhibition and/or deletion of PARP1 or USP3 restores transcriptional recovery in XRCC1−/− cells, highlighting PARP1 and USP3 as possible therapeutic targets in neurological disease." (PMID 34811483, 2021). "Importantly, either PARP1 or USP3 inhibition/depletion rescue normal levels of histone monoubiquitination and transcription recovery following DNA base damage, highlighting these enzymes as possible therapeutic targets in the treatment of base excision repair (BER)-defective neurological disease." (PMID 34811483, 2021).
USP3 also shares sentences with these, for which no sentence is quoted: lung carcinoma (2 papers); osteoarthritis (2); hepatoma (1); metastasis (1); neuronal tumor (1); Pan (1); stomach cancer (1).